AQP4 (aquaporin 4)
Diseases named in the same sentence as AQP4 in open-access papers (continued):
Sharing a sentence is not in itself a finding about the gene and the disease.
experimental autoimmune encephalomyelitis (23 papers, 2009 to 2025). An autoimmune demyelinating disease of the central nervous system that is produced experimentally in animals by the injection of homogenized brain or spinal cord in Freund's adjuvant. "The pathogenicity of antibodies against MOG and AQP4 was shown using variants of rat experimental autoimmune encephalomyelitis (EAE)." (PMID 37499337, 2023). "The Lewis rat model of NMO uses a myelin-reactive experimental autoimmune encephalomyelitis (EAE) background with passive transfer of pooled human antibody from patients with aquaporin-4 (AQP4) seropositive NMO at onset of EAE symptoms." (PMID 30648122, 2018). "Passive transfer of IgGs from NMO patients to experimental autoimmune encephalomyelitis rats reduced the expression of AQP4 in astrocytes coupling with severer clinical neurological functions." (PMID 28174515, 2017). "Initial models involved administration of AQP4-IgG to rats with pre-existing neuroinflammation produced by experimental autoimmune encephalomyelitis." (PMID 27905992, 2016). "In agreement with the present finding, reduced reactive astrogliosis and microgliosis is also observed in AQP4−/− mice in experimental autoimmune encephalomyelitis and after intracerebral injection of LPS." (PMID 26526066, 2015). "Recent data in a model of experimental autoimmune encephalomyelitis (EAE) in which homogenized guinea-pig whole spinal cord was injected into rats showed upregulation of AQP4 starting at 10 days until the onset and peak of cerebellar enlargement." (PMID 23270503, 2012). "We investigated the involvement of AQP4 in disease severity in an established mouse model of experimental autoimmune encephalomyelitis (EAE) produced by immunization with myelin oligodendrocyte glycoprotein (MOG35–55) peptide." (PMID 19660138, 2009). "Experimentally, NMOSD-ON has been mimicked in vivo by transfer of human AQP4-IgG to animals with pre-established experimental autoimmune encephalomyelitis (EAE) or by direct intracerebral injection near the optic chiasma together with human C via continuous infusion using an implanted mini-pump." (PMID 34367056, 2021). "Similarly, neuroinflammation induced by lipopolysaccharide (LPS) or experimental autoimmune encephalomyelitis (EAE) was attenuated in AQP4 KO mice, showing the neuroprotective effect of AQP4 deficiency." (PMID 32398151, 2020). "In experimental autoimmune encephalomyelitis, the standard murine model of MS, aquaporin 4 expressing Müller cells are mandatory for the integrity of the blood-retinal-barrier and genetic ablation of aquaporin-4 may result in altered retinal perfusion." (PMID 38090586, 2023). "We directly compared MOG35–55-induced experimental autoimmune encephalomyelitis exacerbated by MOG- and AQP4-IgG (versus isotype IgG, Iso-IgG)." (PMID 37499337, 2023). "Using the murine MS model of experimental autoimmune encephalomyelitis, we could recently show that aquaporin-4 expressed by retinal Müller cells is essential for the integrity of the gliovascular unit and that genetic ablation of aquaporin-4 results in a disturbed retinal perfusion." (PMID 36439131, 2022). "Recently, increased AQP4 expression was found in brain and spinal cord in experimental autoimmune encephalomyelitis (EAE), providing further support for the possible involvement of AQP4 in CNS inflammation." (PMID 19660138, 2009). "Traditional experimental models, including passive transfer of AQP4-IgG with complement, AQP4-specific T cells, or experimental autoimmune encephalomyelitis (EAE)-based models, provide insights but failed to fully recapitulate human NMOSD ON pathology." (PMID 41227356, 2025).
cerebral infarction (21 papers, 2010 to 2025). An ischemic condition of the brain, producing a persistent focal neurological deficit in the area of distribution of the cerebral arteries. "AQP4 is expressed at astrocyte endfeet to regulate water transport to the brain parenchyma, as its absence has ameliorated brain edema induced by brain infarction and exacerbated the recovery of brain edema caused by vascular inflammation." (PMID 27258268, 2016). "In cerebrally infarcted rats, Klotho has also been shown to improve neurological function, reduce ischemic injury, and reduce the area of cerebral infarction by inhibiting the p38 MAPK pathway by downregulating the expression of aquaporin 4 (AQP4)." (PMID 39308872, 2024). "Prior research has noted heightened AQP4 expression post-cerebral infarction, and AQP4 inhibition has been demonstrated to exert protective effects in models of cerebral infarction." (PMID 37695472, 2024). "Brain infarction and edema were assessed, and Western blot analyses were conducted to examine the expression levels of aquaporin-4 (AQP4), metalloproteinase-9 (MMP-9), and the neurovascular tight-junction protein ZO-1 upon sacrifice." (PMID 39457496, 2024). "The inhibition of aquaporin 4 (AQP4) expression by statins has also been shown to contribute to the reduced volume of cerebral infarction by suppressing brain edema." (PMID 35215263, 2022). "Studies from cerebral infarction patients demonstrated that AQP4 expression increased only in white matter, while cortical astrocytes exhibited reduced perivascular AQP4." (PMID 34305569, 2021). "Then cell counting kit-8 assay, flow cytometry analysis, Triphenyltetrazolium chloride (TTC) staining, and western blotting were used to determine cell viability, cell apoptosis, cerebral infarction volume, and the abundance of AQP4, respectively." (PMID 32138732, 2020). "Compared with the GR group, the GR + CBX group significantly improved in NDS (P < 0.05), and decreased the percentage of the cerebral infarction area (P < 0.05) and expression of Cx43 and AQP4 protein (P < 0.05)." (PMID 31572219, 2019). "In fact, AQP4 has been shown to modulate water transport at the blood-brain barrier (BBB) to aggravate brain edema after brain infarction but also to facilitate the recovery from vasogenic brain edema, although its absence does not change BBB morphology." (PMID 27258268, 2016). "Additionally, treadmill exercise has been found to influence the polar expression of AQP4 in rats with local cerebral infarction." (PMID 41009480, 2025). "It has been suggested that suppression of aquaporin-4 function may be an effective treatment for reducing cellular edema after cerebral infarction." (PMID 34617156, 2021). "Moreover, enhanced AQP4 expression is found in reactive astrocytes in cerebral infarction ischemic lesions, suggesting a compensatory upregulation of AQP4 to counter the water imbalance." (PMID 21119881, 2010). "The glymphatic function in the cortex surrounding cerebral infarction was determined using tracer, glial fibrillary acid protein (GFAP), AQP4 co-staining, and beta-amyloid precursor protein (APP) staining; differential genes were detected using RNA-seq." (PMID 37695472, 2024). "In vivo experiments also confirmed that AQP4 inhibitor TGN‐020 reduced and overexpression of AQP4 increased behavioral abnormalities and brain infarcts." (PMID 39444081, 2024). "The present experimental results found that CBX can inhibit GJ, reduce the expression of both the Cx43 and AQP4 protein, improve the NDS and reduce the percentage of the cerebral infarction area." (PMID 31572219, 2019). "In a cerebral infarction model, TGN-020, an AQP4 inhibitor, alleviated CSF-derived cerebral edema." (PMID 40012567, 2025).
injury (21 papers, 2009 to 2025). Damage inflicted on the body as the direct or indirect result of an external force, with or without disruption of structural continuity. "Furthermore, previous studies have indicated that increases in Aqp4 expression are associated with blood brain barrier leakage, astrogliosis, and microglial activation in the context of brain injury." (PMID 28148272, 2017). "AQP4 is the most abundant aquaporin in the CNS, and studies have found that inhibition of AQP4 expression can reduce the degree of cerebral edema, inflammatory response and apoptosis in traumatic brain injury." (PMID 40406486, 2025). "A previous study showed that AQP4 promoted cytotoxic edema in astrocytes, playing a critical role in the pathogenesis of traumatic brain injury." (PMID 38391735, 2024). "Earlier research has established that AQP1, AQP4, AQP2 and AQP9 are associated with spinal cord injury- or nerve injury-induced nerve pain in rats." (PMID 35324416, 2022). "Due to its role in brain water balance, AQP4 is believed to play an important role in development of brain edema, which is supported by increased survival rates of AQP4 knock-out mice following traumatic brain injury." (PMID 29077056, 2017). "Relcovaptan is known to downregulate Aqp4 after brain injury." (PMID 41509943, 2025). "Similar effects of drugs on AQP4 translocation were observed between hypotonic and hypoxic conditions, confirming that hypotonicity is appropriate to model the hypoxic conditions relevant to brain trauma when studying AQP4 translocation mechanisms." (PMID 38102893, 2024). "A previous study reported that inhibition of p38 MAPK signaling could decrease AQP4 expression, which plays an important role in cerebral edema in traumatic brain injury." (PMID 38391735, 2024). "However, the FO supplementation was shown to suppress Aqp4 expression in the model of traumatic brain injury." (PMID 39273347, 2024). "Collectively, these results suggest that glutamate induces cell swelling and alters AQP4 expression in astrocytes via mGluR5 activation, which may provide a novel approach for the treatment of edema following brain injury." (PMID 28503134, 2017). "This disparity may be attributable to changes in AQP4 or TJ protein expression between ages, as juveniles have been reported to have delayed increases in AQP4 and preserved expression of collagen-IV, laminin, claudin-5, occludin, and ZO-1 following brain injury." (PMID 32397302, 2020). "It has been suggested that AQP4 plays an important role in BBB function and in the pathogenesis of hypertensive cerebral injury." (PMID 32120798, 2020). "The target antigen of NMO-IgG is aquaporin 4 (AQP4), glial water channel protein, that facilitates water transport, especially in "stress situations" such as brain injury." (PMID 19852774, 2009). "Based on the functional interaction between AQP4 and NKCC1 in the central nerve system, it was shown beneficial to simultaneously inhibit injury-induced upregulation of AQP4 and NKCC1 after traumatic brain injury." (PMID 29403391, 2018). "It has been demonstrated that there is a downregulation of AQP4 (normalization) after CURC administration in different neurological injury and brain damage models like: traumatic brain injury, hypoxia–ischemic brain damage, hypoxia-hypercapnia-induced brain damage, and spinal cord injury." (PMID 29292793, 2017).
breast carcinoma (17 papers, 2012 to 2025). "Two 18q11.2 genetic variants (CHST9 rs1436904 and AQP4 rs527616) were identified as novel breast cancer susceptibility components based on GWAS24." (PMID 28924212, 2017). "Paradoxically, in our analysis, breast cancer and lung cancer are the most common tumor types in patients with AQP4‐positive paraneoplastic NMOSD, which may be associated with their high incidence." (PMID 34520629, 2021). "Based on a breast cancer GWAS, which identified AQP4 rs527616 and CHST9 rs1436904 genetic variants, we explored their involvement in early-stage TNBC and concluded that the CHST9 rs1436904 SNP is an independent prognostic genetic variant in Chinese TNBC patients." (PMID 28924212, 2017). "In various studies related to non-alcoholic steatohepatitis, resistance to Adriamycin in breast cancer, and ischemic injury, Gsk3b and Aqp4 have been identified as direct target genes of miR-29a-3p." (PMID 40529227, 2025). "A history of a prior malignant disorder was found in two patients: one AQP4+ patient with breast cancer and one double-seronegative patient with cervix cancer." (PMID 38256489, 2024). "Actually, an aquaporin model has been previously proposed to explain the selectivity of CAP against cancer cells, where AQP1/3/5 were over-represented and AQP4 was under-expressed in breast cancers." (PMID 35637961, 2022). "AQP4 was found to be highly expressed in a variety of tumor cells including lung cancer and breast cancer and can promote tumor progression, invasion, and metastasis." (PMID 34520629, 2021). "The expression of AQP4 was low in breast cancer and gastric cancer, but high in lung cancer, meningiomas, and thyroid carcinoma." (PMID 34520629, 2021). "The occurrence of AQP4‐positive NMOSD was associated with a wide range of cancer types, especially breast cancer and lung cancer." (PMID 34520629, 2021). "Four per cent of our patients had a history of cancer, including breast cancer, cervical cancer, rectal cancer, nasopharyngeal cancer, and skin cancer, all of whom were positive for AQP4-Ab." (PMID 22260418, 2012). "Besides, in breast cancer, thyroid carcinoma (undifferentiated), and stomach cancer, the expression of AQP4 is low." (PMID 36203529, 2022). "Next, we outline the roles in breast cancer of AQP1, AQP3, AQP4, AQP5, and AQP7, which are the only AQPs that have begun to be characterized as having roles in breast cancer progression and as potential prognostic markers." (PMID 36212456, 2022). "The mRNA expression levels of AQP8, AQP9, and AQP10 were upregulated, while those of AQP3, AQP4, AQP5, and especially AQP7, were downregulated in breast cancer based on the Oncomine database." (PMID 36212456, 2022). "As found for OIS, TIS also reduced TR on both the UGA and the AQP4 reporters and similar results were found in MDA.MB.231 breast cancer cells." (PMID 34676390, 2021). "AQP1, AQP3, AQP4, AQP5, AQP7, and AQP9 expression were evaluated because these AQPs are expressed in breast tumors and have begun to be characterized as having roles in breast cancer progression and metastasis." (PMID 39123442, 2024). "In this review, we discuss the roles of AQP1, AQP3, AQP4, AQP5, and AQP7 in breast cancer progression and metastasis, including the role of AQPs in the tumor microenvironment, to highlight potential contributions of stromal-derived to epithelial-derived AQPs to breast cancer." (PMID 36212456, 2022).
cerebral amyloid angiopathy (17 papers, 2015 to 2024). "Our previous study also showed that knocking out the Aqp4 gene exacerbates brain Aβ deposition and cerebral amyloid angiopathy in APP/PS1 mice." (PMID 30867902, 2019). "Follow-up of that finding by the NMU group documented that Aβ accumulation and cerebral amyloid angiopathy were significantly increased in a double-hit murine model with Aqp4 deletion and Aβ over-expression." (PMID 30561329, 2018). "On autopsy, higher AQP4 expression was found in the brain tissue of patients with AD and cerebral amyloid angiopathy (CAA) than in that of controls, suggesting that AQP4 may play a role in the damage of water transport in AD and CAA." (PMID 35111362, 2022). "Aβ accumulation in capillaries, associated with cerebral amyloid angiopathy (CAA), also affect NVU astrocytes to cause mislocalization of AQP-4 expression, which was consistent with the acute accumulation of Aβ around swelling astrocytic endfeet as shown in our present study." (PMID 34975487, 2021). "Here, we reported that the deletion of AQP4 exacerbated cognitive deficits of 12-moth old APP/PS1 mice, with increases in Aβ accumulation, cerebral amyloid angiopathy and loss of synaptic protein and brain-derived neurotrophic factor in the hippocampus and cortex." (PMID 26526066, 2015). "Moreover, end-feet inward rectifying potassium channel, Kir 4.1 and BK calcium-dependent potassium channel, being tightly co-anchored to aquaporin-4-water channels, have been found significantly decreased in mice with high levels of cerebral amyloid angiopathy." (PMID 32046035, 2020). "Deleting AQP4 from APP/PS1 mice resulted in increased accumulation of amyloid both as plaques in parenchyma and as cerebral amyloid angiopathy (CAA) around blood vessels, as well as increased soluble Aβ levels." (PMID 32398151, 2020). "Nonetheless, increased expression of AQP4 was observed in patients with AD with or without cerebral amyloid angiopathy (CAA), where extensive AQP4 immunoreactivity was seen around blood vessels in the CSF and brain interfaces." (PMID 27420057, 2016). "In addition to the brain parenchyma, Aβ deposition manifested in cortical and leptomeningeal vessels as cerebral amyloid angiopathy (CAA), which was also increased in the AQP4−/−APP/PS1 mice." (PMID 26526066, 2015). "In addition, hippocampal capillary and AQP4 densities were indistinguishable between HCHF-fed TgAD and nTg rats despite the AD pathology progression at 15 months (specifically, the increase in cerebral amyloid angiopathy in females)." (PMID 39659583, 2024).